AFP (alpha fetoprotein)
Diseases named in the same sentence as AFP in open-access papers (continued):
Sharing a sentence is not in itself a finding about the gene and the disease.
metastatic disease (28 papers, 2011 to 2025). "Higher age (≥8 years), low AFP (<100 ng/ml) and metastatic disease significantly increased risk for OS-event." (PMID 33312943, 2020). "Due to the non-specific clinical presentation of HCO and the fact that elevated AFP levels can be observed in various ovarian and metastatic tumors, establishing a differential diagnosis can be highly challenging." (PMID 40919162, 2025). "After 8 weeks of routine follow-up, the patient was found to have a rising AFP and relapsed metastatic disease by surveillance imaging." (PMID 38727682, 2024). "We statistically analyzed the age, sex, PRETEXT stage, pathologic type, metastatic disease, serum AFP level, vascular involvement, and surgical margin status of all children with initial CR." (PMID 34843510, 2021). "We assessed age, sex, PRETEXT stage, pathologic type, metastatic disease, serum AFP level, vascular involvement, and surgical margin status of 140 children who achieved initial CR with a multivariate Cox regression model." (PMID 34843510, 2021). "Variables consisted of age, sex, PRE-Treatment EXTent of tumor (PRETEXT) stage, pathologic type, metastatic disease, serum alpha-fetoprotein level, vascular involvement, and surgical margin status." (PMID 34843510, 2021). "CHIC-HS has not only confirmed the prognostic importance of factors such as metastatic disease, low AFP concentration (≤100 ng/ml), and PRETEXT group, that were originally proposed but also suggested additional new prognostic factors and more detailed grouping criteria." (PMID 33312943, 2020). "In terms of risk factors associated with poor outcomes, his AFP level at diagnosis did not place him in the unfavorable category; however, he had metastatic disease and was older than 5 years." (PMID 28079820, 2017). "Second, we found that Black patients have more advanced HCC, as evidenced by larger tumors, a higher percentage of poorly differentiated tumors, tumors with gross and microscopic vascular invasion, higher AFP levels, and a higher prevalence of metastatic disease, as we hypothesized." (PMID 38230878, 2024). "Thus, a complete response to the treatment should be expected if previous levels of AFP were lower than normal values on follow-ups, while a novel elevation of AFP after treatment may suggest tumour recurrence or metastatic disease." (PMID 35497085, 2022). "At the time of HCC diagnosis, univariate regression analysis identified tumor growth pattern, extrahepatic metastatic disease, therapy, Albumin-Bilirubin (ALBI) grade, alpha-fetoprotein (AFP), and BMD as prognostic factors for median OS." (PMID 40845067, 2025). "Ovarian cystadenocarcinoma usually occurs at an older age, and serum AFP is negative, whereas metastatic tumors have a history of primary malignancy in other organs." (PMID 38966065, 2024). "Post-orchiectomy, AFP levels are anticipated to normalize in most patients by 4 to 5 half-lives or approximately one month, in the absence of persistent or metastatic disease." (PMID 39685906, 2024). "If AFP levels do not decrease by postoperative day 5, residual tumor or metastatic disease should be considered." (PMID 25547829, 2014). "Immunohistochemical examination demonstrated that the tumor cells were positive for glypican-3 (GPC3), alpha-fetoprotein (AFP), hepatocyte paraffin-1 (Hep Par 1), cytokeratin 18 (CK 18), and hepatocyte antigen, which confirmed that the seminal vesicle tumor was a metastatic tumor of HCC." (PMID 21443783, 2011).
metastasis (27 papers, 2011 to 2025). The spread or migration of cancer cells from one part of the body (where they first appeared) to another. "In the training cohort, univariate analysis showed that sex, marital status, AJCC stage, tumor size, T stage, bone metastasis, lung metastasis, AFP level, fibrosis score, surgery, and chemotherapy were risk factors for CSS in patients with HCC (P < .05)." (PMID 39312373, 2024). "We found that AFP ≥ 200 ng/ml was an independent risk factor for the liver metastasis of APA-GI (hazard ratio 4.55, 95% confidence interval 1.39–14.87, P = 0.012)." (PMID 33996549, 2021). "This hepatoid GC and AFP-GC exhibit a high frequency of vascular invasion, lymph node and liver metastasis, and poor prognosis." (PMID 37588998, 2023). "These attributes including age, sex, marital status, T stage, N stage, surgery, chemotherapy, tumor size, alpha-fetoprotein level, fibrosis score, bone metastasis, lung metastasis, and grade were the independent prognostic factors for older patients with HCC while predicting survival duration." (PMID 37067674, 2024). "The high probability of vascular invasion in AFP-positive GC may play as an important role in the occurrence of liver metastasis and poor prognosis." (PMID 35847953, 2022). "Univariate analysis identified AFP, M stage, TNM stage, liver metastasis, surgical type, tumor composition, PNI, LVI, and adjuvant chemotherapy as significant prognostic factors." (PMID 41333214, 2025). "Lung metastasis also indicated higher death rate (p < 0.001), higher GGT (p = 0.024) and higher AFP (p = 0.049)." (PMID 38818476, 2024). "Immunohistochemistry showed that Cx43 expression in patients with low AFP was lower in patients with distant metastases than in those with no metastasis or those with liver metastasis." (PMID 23800357, 2013). "However, they pointed out that liver metastasis was the only independent prognostic factor in AFP-positive GC and AFP-positivity was not an independent prognostic factor." (PMID 35847953, 2022).
alcoholism (25 papers, 2012 to 2026). "After adjustment of other relevant variables, some factors showed insignificant associations, including race, HCV genotype, alcoholism, and serum alpha-fetoprotein levels." (PMID 35095765, 2021). "The results showed that a history of alcoholism and serum levels of AFP, TP and GGT were independently associated with the 1-year recurrence rate of HBV-related HCC in patients treated for a single small primary tumor." (PMID 31413831, 2019). "A history of alcoholism and serum levels of AFP, TP and GGT were independently associated with the 1-year recurrence rate of HBV-related HCC in patients with a single small (≤3 cm) primary tumor." (PMID 31413831, 2019). "In addition to King’s score, tumor size, high AFP and alcoholism are also independent predictors associated with tumor recurrence." (PMID 29555927, 2018). "In univariate analysis, positive HBsAg, alcoholism, high AFP, tumor number > 3 nodules, tumor size > 3 cm, presence of vascular invasion and King’s score grade 3 were associated with increased risk of recurrence (all p < 0.05)." (PMID 29555927, 2018). "Patients with HBV-related HCC who had a single small primary tumor were included in the present study; the results showed that AFP, GGT and a history of alcoholism were independent risk factors for HCC recurrence within 1 year after surgery, while TP was a protective factor." (PMID 31413831, 2019). "In univariate survival analysis, alcoholism, presence of ascites, alkaline phosphatase level, serum platelet count and AFP level, maximum tumor diameter, vascular invasion, performance status and ALBI grade were the factors associated with a poor prognosis (all p values <0.05)." (PMID 28672011, 2017). "The results of the univariable Cox regression analyses showed that a history of alcoholism, serum levels of GGT, AFP and TP, and blood levels of CD8+ T lymphocytes were associated with 1-year HCC recurrence rate." (PMID 31413831, 2019). "On the contrary, the HCV and alcohol‐related HCC exhibit a nonproliferation phenotype with moderately‐to‐well differentiation, lower serum AFP levels, and higher CTNNB1 and TERT promoter mutation." (PMID 40948427, 2025). "Univariate survival analysis show that DM, age, gender, HBV, alcoholism, albumin, bilirubin, INR, Na, AFP, eGFR, variceal bleeding, total tumor volume, vascular invasion, presence of ascites, and platelet count were significant predictors for survival in HCC patients (all p< 0.05)." (PMID 28333991, 2017). "The Cox regression equation was: recurrence score (RS) = 0.595 × history of alcoholism (yes, 1; no, 0) + 0.006 × GGT − 0.041 × TP + 0.729 × AFP (positive, 1; negative, 0)." (PMID 31413831, 2019).
preeclampsia (25 papers, 2014 to 2025). Preeclampsia is a hypertensive disorder of pregnancy that is characterized by new-onset hypertension with proteinuria presenting after 20 weeks of gestation, and depending on mild or severe forms may initially present with severe headache, visual disturbances, and hyperreflexia. "We identified that PEGIL11 treatment significantly regulated the placental production of multiple factors previously associated with preeclampsia including alpha-fetoprotein, angiotensinogen, apolipoproteins A1 and B, and vitamin D receptor." (PMID 37292200, 2023). "The relationship between the AFP increase in the second trimester and pregnancy complications (such as gestational hypertension, preeclampsia, fetal loss, preterm delivery, IUGR, placental abruption, and bleeding) has also been established." (PMID 35425672, 2022). "Emerging evidence suggests that changes in AFP expression and release may influence the composition of cfDNA, and reduced AFP levels have been associated with a lower risk of preeclampsia and preterm birth." (PMID 40837189, 2025). "Furthermore, adverse pregnancy outcomes such as preeclampsia, premature birth, placental abruption and fetal demise have been shown to be associated with unexplainably high AFP in pregnancies." (PMID 36556136, 2022). "First trimester median MoM values of AFP increased in the all PE, gestational hypertension and preterm birth groups." (PMID 35260099, 2022). "Elevated AFP and hCG have been associated with low birthweight, IUGR, preeclampsia, as well as fetal stillbirth and preterm birth." (PMID 35425672, 2022). "It is well known that second-trimester maternal serum alpha-fetoprotein (MS-AFP) is a predictor for adverse pregnancy outcomes (APOs), such as preterm birth, stillbirth, preeclampsia and small for gestational age (SGA)." (PMID 32050927, 2020). "A significant relationship was found between the high levels of maternal serum AFP and hCG MoM and poor pregnancy outcomes like preeclampsia, IUGR, PPROM, intrauterine fetal death (p=0.003, p=0.001, p=0.040, p=0.006)." (PMID 28913007, 2014). "The combination of D-dimer, alpha-fetoprotein, and free beta-hCG demonstrated higher screening efficiency than the traditional alpha-fetoprotein and free β-hCG model, with a receiver operating characteristic (ROC) > 0.800 for severe preeclampsia, preeclampsia, and gestational hypertension." (PMID 40585732, 2025). "Participants with preeclampsia were found to have significantly higher AFP levels." (PMID 37685488, 2023).
Thrombocytopenia (25 papers, 2010 to 2025). A reduction in the number of circulating thrombocytes. "Platelet count was also lower, with more significant thrombocytopenia (median =113000/mm3) associated with high AFP levels." (PMID 32341704, 2020). "In the univariate analysis of patients including the PALBI grade, thrombocytopenia, lower albumin levels, higher creatinine levels, ascites, AFP > 200 ng/mL, vascular invasion, larger tumor size, performance status 2 and PALBI grades 2–3 were associated with decreased long-term survival." (PMID 37046586, 2023). "In the univariate analysis of patients including the MELD score, thrombocytopenia, lower albumin levels, higher creatinine levels, ascites, AFP > 200 ng/mL, vascular invasion, larger tumor size, performance status 2 and MELD score > 8 were associated with decreased long-term survival." (PMID 37046586, 2023). "In the univariate analysis of patients including the PAL grade, thrombocytopenia, lower albumin levels, higher creatinine levels, ascites, AFP > 200 ng/mL, vascular invasion, larger tumor size, performance status 2 and PAL grades 2–3 were associated with decreased survival." (PMID 37046586, 2023). "Also, it seems that there is a connection between the AFP level and thrombocytopenia, a phenomenon incompletely studied." (PMID 32341704, 2020). "Furthermore, the patients in the MAFLD group had a lower frequency of thrombocytopenia, lower serum AFP, a higher proportion of well differentiation tumors, and a lower proportion of microvascular invasion, which are so-called ‘positive’ factors for better outcomes in HCC." (PMID 34442328, 2021). "Thus, our predictive model combining thrombocytopenia and high AFP levels could have potential clinical application in the future." (PMID 33289529, 2021). "INR was raised (1.4; normal range 0.8–1.2) and did not respond to vitamin K. He also had a persistent thrombocytopenia (lowest value 59 109/L) with otherwise normal blood parameters and raised alpha‐fetoprotein of 8820 μg/L (normal range < 10)." (PMID 36636598, 2023).
neural tube defect (23 papers, 2004 to 2025). A congenital defect characterized by failure of the neural tube to close completely; this results in the presence of openings in the brain or spinal cord. "Seven mothers underwent a serum screening test together, and two of them showed values of 2.725 and 2.90 for neural tube defects, but a low-risk result was obtained in the AFP test." (PMID 37888079, 2023). "Since the introduction of alpha-fetoprotein screening in the late 1970s to identify women at increased risk of having a fetus with a neural tube defect (NTD), an association has been found accompany with pregnancy complications." (PMID 35317005, 2022). "In the past, all women with elevated MSAFP were offered amniocentesis as the diagnostic test, since elevated levels of amniotic fluid AFP together with elevated acetyl cholinesterase are considered to be diagnostic for fetal NTD (neural tube defect)." (PMID 23329921, 2011). "The most common association related to alpha-fetoprotein (AFP) is fetal neural tube defect (NTD), and indeed, this is where the international career of this protein began." (PMID 38256600, 2024). "In the 1970s and 1980s, the sensitivity of ultrasound examinations in detecting neural tube defects was so low that the combination of AFP and acetylcholinesterase determination in amniotic fluid was the primary diagnostic marker for NTD." (PMID 38256600, 2024). "On the other hand, PAPP-A, free β-hCG and nuchal translucency (NT) in the first-trimester and UE3, inhibin-A, HCG and AFP in the second trimester predict aneuploidy, Neural Tube Defect (NTD) and high-risk pregnancy." (PMID 37605237, 2023). "Report of U.K. collaborative study on alpha-fetoprotein in relation to neural-tube defects Maternal serum-alpha-fetoprotein measurement in antenatal screening for anencephaly and spina bifida in early pregnancy." (PMID 41466741, 2025). "Neural tube defects were first diagnosed prenatally in the 1970s with the discovery of elevated concentrations of alpha-fetoprotein in amniotic fluid samples from pregnancies with anencephaly or MMC." (PMID 39835283, 2025). "A breakthrough discovery in the 1970s was the determination of alpha-fetoprotein levels in the serum of pregnant women to detect fetuses with neural tube defects." (PMID 38256600, 2024). "Prenatal genetic testing started in the mid‐1970s with the introduction of the first serum analyte alpha‐fetoprotein (AFP) screening for neural tube defects." (PMID 40496519, 2024). "Measurements of AFP in amniotic fluid and MS were first introduced in the 1970s as an aid to the diagnosis and of neural tube defects." (PMID 39004916, 2024). "Screening the serum of pregnant women at 16 to 18 weeks' gestation for alpha-fetoprotein can result in the detection of about 80% of fetuses with anencephaly and other neural tube defects." (PMID 20181096, 2010). "Significant elevations of amniotic fluid and maternal serum alpha-fetoprotein (MSAFP) have been shown to be associated with spina bifida and other neural tube defects (NTD)." (PMID 15352998, 2004). "Alpha-fetoprotein (AFP) in maternal serum, assessed during the second trimester, is used to screen for neural tube defects (NTDs)." (PMID 41590228, 2025). "By testing a combination of maternal serum levels of AFP, uE3, HCG, and PAPP-A, doctors can screen for antenatal aneuploidy diseases, including Down syndrome, trisomy 18 syndrome, and neural tube defects (NTD)." (PMID 35712096, 2022). "Besides though test results were not in risk area for trisomy, it was detected that structural fetal anomalies such as open neural tube defect (NTD), abdominal wall defect and placental anomalies were accompanied by high AFP and\or high hCG levels." (PMID 28913007, 2014). "AFP levels in amniotic fluid and maternal serum can be abnormally increased in many fetal defects, making AFP and some of its glycosylated isoforms a sensitive but not specific marker of neural tube defects." (PMID 37108840, 2023).